ASMTL-AS1 (ASMTL antisense RNA 1)
Synonyms: FLJ13330; formerly CXYorf2; NCRNA00105; ASMTLAS; ASMTL-AS
Gene: Long non-coding RNA gene on chromosome X (1,401,430 to 1,414,028, forward strand). Ensembl gene ENSG00000236017.
Diseases named in the same sentence as ASMTL-AS1 in open-access papers:
ASMTL-AS1 is named in the same sentence as 3 diseases in open-access papers, as found by Europe PMC text mining. Sharing a sentence is not in itself a finding about the gene and the disease. The quoted sentences say what the papers report.
breast carcinoma (1 paper, 2022). "Moreover, ASMTL-AS1, a noncoding transcript, inhibits β-catenin expression and inactivates carcinogenic Wnt/β-catenin signaling in breast cancer." (PMID 35680563, 2022).
tumour (1 paper, 2020). "For example, some lncRNAs, such as NOC2L-4.1, TUG1, and MALAT1, are well established to promote tumour growth, while other lncRNAs, such as ASMTL-AS1, LINC02381, and LINC02499 have been found to inhibit tumour progression." (PMID 33243205, 2020).
ASMTL-AS1 also shares sentences with these, for which no sentence is quoted: colorectal cancer (1 paper).